KLHDC8A (kelch domain containing 8A)
Synonyms: FLJ10748
Tractability: No criterion of Open Targets' tractability assessment is met for any kind of drug.
Gene: Protein-coding gene on chromosome 1 (205,336,061 to 205,357,324, reverse strand). Ensembl gene ENSG00000162873.
Subcellular location (Human Protein Atlas): Nucleoplasm; Cytosol
Gene Ontology:
Molecular function: protein binding
Genetic constraint (gnomAD): Loss-of-function variants: 21 observed, 34.45 expected, observed/expected ratio (o/e) 0.61, 90% interval 0.43 to 0.88. The upper end of that interval is the gene's LOEUF score, 0.88, which puts it in group 3 of 6, group 1 being the genes least tolerant of losing a copy. Missense variants: 435 observed, 504.71 expected, observed/expected ratio (o/e) 0.86, 90% interval 0.8 to 0.93. Synonymous variants: 173 observed, 203.49 expected, observed/expected ratio (o/e) 0.85, 90% interval 0.75 to 0.96.
Homologues: Orthologues: chimpanzee KLHDC8A (100% identical), macaque KLHDC8A (99% identical), pig KLHDC8A (98% identical), guinea pig KLHDC8A (97% identical), mouse Klhdc8a (96% identical), rat Klhdc8a (96% identical), rabbit KLHDC8A (95% identical), dog KLHDC8A (95% identical), tropical clawed frog klhdc8a (74% identical). Paralogues in human: KLHDC8B (46% identical), KLHL8 (27% identical), KLHL10 (26% identical), KLHL28 (25% identical), KLHL12 (25% identical), IPP (24% identical), KLHL1 (24% identical), KLHL20 (24% identical), KLHL4 (24% identical), KLHL18 (24% identical), KLHL3 (24% identical), KLHL29 (24% identical), and 42 more.
Diseases named in the same sentence as KLHDC8A in open-access papers:
KLHDC8A is named in the same sentence as 7 diseases in open-access papers, as found by Europe PMC text mining. Sharing a sentence is not in itself a finding about the gene and the disease. The quoted sentences say what the papers report.
glioma (10 papers, 2019 to 2025). A benign or malignant brain and spinal cord tumor that arises from glial cells (astrocytes, oligodendrocytes, ependymal cells). "We also investigated the contribution of KLHDC8A to the function of glioma cells and the underlying mechanism." (PMID 32851798, 2020). "As discussed, KLHDC8A is linked to glioma, indicating a possible role in neurological malignancies." (PMID 39887712, 2025). "Our findings provide the role of KLHDC8A in the pathogenesis of glioma and KLHDC8A may be a potential diagnostic and prognostic marker." (PMID 32851798, 2020). "KLHDC8A has been proved to be highly expressed in glioma and associated tumour growth." (PMID 32851798, 2020). "Meanwhile, KLHDC8A knockdown also caused a decrease in glioma cell colony formation." (PMID 32851798, 2020). "The study showed that upregulation of KLHDC8A promotes glioma cell proliferation, migration and invasion while inhibiting apoptosis." (PMID 39887712, 2025). "Both KLHDC8A and KLHDC8B have been implicated in glioma cell apoptosis and classical Hodgkin lymphoma, respectively." (PMID 39887712, 2025). "KLHDC8A is significantly overexpressed in high‐grade gliomas compared to low‐grade and normal brain tissues." (PMID 39887712, 2025). "A recent study showed glioma ciliation is linked to glioma cell stemness and thru the master transcriptional regulator SOX2 and superenhancer KLHDC8A expression." (PMID 38630257, 2023). "The proliferation, migration, and invasion of glioma cells are all triggered by the overexpression of KLHDC8A." (PMID 37238995, 2023). "Macrophages, neutrophils, regulatory T cells, the immunological checkpoint PD-L1, and KLHDC8A expression were all highly expressed in gliomas." (PMID 37238995, 2023). "As expected, the glioma cells stimulated with gradient concentrations of glucose (0‐4.5 mg/mL) showed a significant increase in the expression of KLHDC8A." (PMID 32851798, 2020). "And the molecular mechanism of KLHDC8A in the regulation of glioma development was further investigated." (PMID 32851798, 2020). "When KLHDC8A overexpressed glioma cells were pretreated with ERK inhibitor U1026 and p38 MAPK inhibitor SB203580,26, 27 phosphorylation of ERK and p38 MAPK was depressed." (PMID 32851798, 2020). "In this study, we detected the KLHDC8A expression in glioma tissues and analysed its relevance with the overall survival of glioma patients." (PMID 32851798, 2020). "The results shown that KLHDC8A expression was up‐regulated in 66 glioma tissues as compared to the 14 normal brain tissues." (PMID 32851798, 2020). "Western blot was used to detect the phosphorylated forms of MAPK family members (ERK1/2, JNK and p38 MAPK), AKT and JAK‐STAT family members (JAK1 and STAT1) in glioma cells which transfected with NC and KLHDC8A siRNA." (PMID 32851798, 2020). "Changes in the expression of proteins related to apoptosis, cell cycle and migration in KLHDC8A‐silenced cells were also consistent with the KLHDC8A function in glioma." (PMID 32851798, 2020). "Mechanistically, KLHDC8A regulated various functions in glioma by directly mediating Bcl2, BAX, p21, CDK2, MMP2 transcription and ERK and P38 MAPK activation." (PMID 32851798, 2020). "Then, we detected the expression of KLHDC8A in glioma and normal brain tissues collected from the Department of Neurosurgery of Yijishan Hospital of Wannan Medical College via RT‐PCR analysis." (PMID 32851798, 2020). "In summary, we have shown that KLHDC8A is up‐regulated in glioma and plays role on cell proliferation, cell cycle and apoptosis as well as migration and invasion." (PMID 32851798, 2020). "We found that KLHDC8A (Kelch domain‐containing 8A) expression level was significantly increased in high‐grade glioma tissues and that high KLHDC8A expression was closely related with poor prognosis." (PMID 32851798, 2020). "In this study, overexpression of KLHDC8A in glioma tissues was confirmed by glioma samples of our hospital, as well as GEPIA and GEO databases." (PMID 32851798, 2020).
glioma (continued). "KLHDC8A overexpression enhances glioma tumorgenesis such as cell proliferation, migration and invasion." (PMID 32851798, 2020). "Meanwhile, the GSE2223 data set demonstrates that KLHDC8A is highly expressed in gliomas and the expression of KLHDC8A in GBM and LGG was higher than normal in GSE4290 data set, respectively." (PMID 32851798, 2020). "Knocking down and overexpressing KLHDC8A in glioma cells indicated that KLHDC8A regulated glioma tumorgenesis, such as proliferation, migration, invasion cell cycle and apoptosis." (PMID 32851798, 2020). "Previous research has shown that KLHDC8A is highly expressed in human gliomas which ΔEGFR was silenced." (PMID 32851798, 2020). "Ablation of KLHDC8A reduced primary cilia, markers of glioma stem cells, and proliferation." (PMID 38630257, 2023). "It is also known that MiR-200b is a regulator of tumor progression and metabolism targeting LDH-A in human malignant gliomas, and that upregulation of KLHDC8A (Kelch domain-containing 8A) is induced by lactate and contributes to the proliferation, migration, and apoptosis of human glioma cells." (PMID 35565435, 2022). "In this study, we determined the relationship of KLHDC8A with MAPK pathways in glioma cells." (PMID 32851798, 2020). "Glioma cell growth was inhibited when the expression of KLHDC8A was knockdown." (PMID 32851798, 2020). "Collectively, we demonstrated that KLHDC8A plays an important role in tumorgenesis of glioma, suggesting that it is a promising prognostic marker and a potential therapy target for the treatment of glioma." (PMID 32851798, 2020). "Using the GEPIA2 database to verify the mRNA expression and its relationship with patient overall survival, we found that the expression of KLHDC8A was significantly increased in glioma vs. controls and correlated with overall survival in patients simultaneously." (PMID 32851798, 2020). "Meanwhile, the KLHDC8A expression which induced by glucose is dependent of LDHA in glioma cells." (PMID 32851798, 2020). "Therefore, we hypothesized KLHDC8A‐promoted glioma cells proliferation, migration and invasion via activating ERK/P38 MAPK pathway." (PMID 32851798, 2020). "However, the function and molecular mechanism of KLHDC8A in glioma remain need further study." (PMID 32851798, 2020). "It has been reported that KLHDC8A overexpression in human gliomas that become resistant to epidermal growth factor receptor (EGFR) silencing (a commonly used anticancer therapeutic approach), allows tumours to maintain aggressiveness through an unknown EGFR-independent pathway." (PMID 30982898, 2019). "It was found that ASPM, CCNB2, HSPG2, KLHDC8A and RRM2 mRNA were differentially expressed in glioma tissues of different grades." (PMID 32667745, 2020). "However, the function and molecular mechanism of KLHDC8A in the development of gliomas are still not clear." (PMID 32851798, 2020).
glioblastoma (3 papers, 2022 to 2025). The most malignant astrocytic tumor (WHO grade IV). "KLHDC8A-correlated genes strongly correlated with hedgehog signaling, angiogenesis, epithelial-to-mesenchymal transition, and hypoxia, which are modulated by signals from the extracellular environment and signals and are molecular processes associated with the progression of glioblastoma." (PMID 36394953, 2023). "In single-cell RNA-Seq data from 28 glioblastoma patients, KLHDC8A was preferentially expressed in neuronal and neoplastic populations, and KLHDC8A expression overlapped with SOX2+ glioblastoma cells." (PMID 36394953, 2023). "Leveraging superenhancer profiling in glioblastoma tissues and GSCs, we identified an epigenetically upregulated gene, KLHDC8A, with expression driven by a superenhancer element located upstream of the gene with contributions from the stemness transcription factor SOX2." (PMID 36394953, 2023). "Here, we interrogated superenhancer landscapes of primary glioblastoma specimens and patient-derived GSCs, revealing a kelch domain–containing gene, specifically Kelch domain containing 8A (KLHDC8A) with a previously unknown function as an epigenetically driven oncogene." (PMID 36394953, 2023). "Collectively, superenhancer-based discovery revealed KLHDC8A as what we believe to be a novel molecular target of cancer stem cells that promotes ciliogenesis to activate the hedgehog pathway, offering insights into therapeutic vulnerabilities for glioblastoma treatment." (PMID 36394953, 2023). "We also examined the effect of GZ17-6.02 on recently identified glioblastoma super-enhancer genes WSCD1, EVOL2, and KLHDC8A as well as the enzyme FADS2, which mediates ELOVL2 signaling." (PMID 35456993, 2022). "KLHDC8A mRNA expression correlated with the IFT88 and ARL13B expression in glioblastoma tissues." (PMID 36394953, 2023). "Furthermore, KLHDC8A expression positively correlated with the expression of SOX2 and OLIG2 in glioblastoma patients from TCGA and CGGA databases." (PMID 36394953, 2023). "KLHDC8A was not a pan-essential gene in a panel of cancer types, which underscores the potential value of targeting KLHDC8A in glioblastoma." (PMID 36394953, 2023). "To determine the specific role of KLHDC8A in glioblastoma, we interrogated the functional importance of KLHDC8A in several nonneoplastic neural cells, including neural stem or progenitor cells (NSCs or NPCs) and nonmalignant neural cells (NMs) derived from epilepsy surgical-resection specimens." (PMID 36394953, 2023).
tumours (6 papers, 2019 to 2023). "A study showed that KLHDC8A was expressed by both tumour cells and macrophages associated with tumours." (PMID 37238995, 2023). "Expression of exogenous KLHDC8A in KLHDC8A-depleted GSCs restored in vivo tumor growth of GSCs." (PMID 36394953, 2023). "Expression levels of seven CBX7 targets, namely Wnt10a, Ccne1, Fgfr2, Bhlhe22, Klhdc8a, Pde10a, and Dusp4, which had been significantly inhibited in miR-181ab1 KO compared to WT tumours in mice, were also significantly lower in either iClust2 or iClust3 than iClust1 HCCs." (PMID 35867177, 2022). "Knockdown of KLHDC8A let to decreased tumorigenicity in ΔEGFR‐independent ‘escaper’ tumours." (PMID 32851798, 2020). "Thus, we interrogated whether disruption of KLHDC8A expression impaired in vivo tumor formation capacity." (PMID 36394953, 2023).
cancer (2 papers, 2019 to 2023). A tumor composed of atypical neoplastic, often pleomorphic cells that invade other tissues. "The hedgehog pathway drives maintenance and migration of cancer stem cells, including in GSCs, so we interrogated the role of KLHDC8A in hedgehog signal transduction in GSCs." (PMID 36394953, 2023). "Among the DENR-regulated transcripts were several relevant to cancer, such as Klhdc8a, Etaa1, Map2k5, Slc20a1 or Vegfd." (PMID 30982898, 2019). "Elevated KLHDC8A expression was associated with sensitivity as measured by AUC with an Aurora B/C kinase inhibitor, a JMJD3 inhibitor, a pan-cancer inhibitor (BRD-4132) with unknown molecular targets, and an insulin-like growth factor 1 receptor (IGF1R) inhibitor." (PMID 36394953, 2023).
KLHDC8A also shares sentences with these, for which no sentence is quoted: epilepsy (1 paper); gout (1); malignant glioma (1).